IL4 (interleukin 4)
Diseases named in the same sentence as IL4 in open-access papers (continued):
Sharing a sentence is not in itself a finding about the gene and the disease.
infection (continued). "IL-4 producing CD4+ T cells were present at the site of infection, indicating that differentiation and migration to site of infection were not a problem." (PMID 21747996, 2011). "Infection of human monocytic cells with mycobacteria in vitro, in the presence of IL-4, appears to promote necrosis over apoptosis in infected cells—a finding consistent with its suggested role as a factor in pathology during M. tuberculosis infection." (PMID 21253484, 2011). "In contrast to IL-17, enhanced induction of IL-4 by the H27 strain was observed 15 d after infection, which coincided with inhibition of IL-17 expression." (PMID 21738761, 2011). "To assess immune responses during vaccination and infection, we measured antigen-specific antibody isotype titres as a surrogate of the underlying CD4+ T cell response, given the known correlation between IL-4 and IgG1 responses and between IFNγ and IgG2a." (PMID 22216363, 2011). "At 6weeks (42 days) after the first infection, 4x mice produced significantly lowerlevels of IL-4 than cells from 1x mice (p<0.05)." (PMID 21445234, 2011). "Intriguingly, expression of an established Th2 cytokine like IL-4 was down-regulated after challenge infection in groups of mice receiving gp63 DNA mixed with CpG either homologously or heterologously." (PMID 21311597, 2011). "Meanwhile, both the inducing cytokines (TGF-β, IL-6, IL-23 and IL-21) and the inhibitory cytokines (IFN-γ and IL-4) of Th17 cell generation all increased after infection." (PMID 22102924, 2011). "While IL-4 mRNA expression was similar in wt and Mif−/− mice at 9 days post infection, IL-10 mRNA expression and protein in ileal mucosa were reduced in Mif−/− compared to wt mice (data not shown)." (PMID 21977228, 2011). "It is therefore, feasible that the observed up-regulation of TFF3 is a response to IL-4 and IL-13 production or mucosal damage following infection." (PMID 21385411, 2011). "In striking contrast, infection with the gal102Δ/Δ strain was characterized by a rapid and increased production of IL-4." (PMID 22114559, 2011). "One hundred percent of the mice infected with dbl-IL-4 survived the infection at both doses (20/20), while 7% (2/30) of mice infected with the dbl-IL-4 + KOS died." (PMID 21139679, 2010). "The IL-4 production was low at 2 weeks of Sj infection, elevated at 7 to 10 weeks of infection and then decreased after 15 weeks of infection." (PMID 20537152, 2010). "Together, these data suggest that the SmCB1-specific IgE response during pre-patent infection is dependent on a concomitant IL-4-producing CD4+ T helper response to worm antigens." (PMID 21078176, 2010). "Accordingly, with the progress of infection, the levels of il4 increased quickly, especially at w 6 post-infection when a large number of eggs appeared, and il10 expression showed a slight elevation." (PMID 23554641, 2010). "Neutralization of IL-4 completely ablated the production of both total and SmCB1-specific IgE at 4 weeks post infection, demonstrating that these responses require IL-4." (PMID 21078176, 2010). "The genes that were suggestive for association with PTB in fetal (IL1A, IL4 and MMP8) and maternal samples (IL-1R2 and IL-6R) in both the MoBa and Cenn studies were mainly infection and inflammation genes (sector D)." (PMID 20140262, 2010). "At 48 h post infection, the levels of IL-4 transcript were similar for all viruses, except vTG3, which appeared higher (48 h)." (PMID 21139679, 2010). "The gB RNA levels followed the same patterns seen for IL-4 RNA, except for vEye2 which had gB RNA levels similar to the parental virus at 24 h post infection." (PMID 21139679, 2010). "Shortly after the beginning of egg deposition, a strong egg-specific Th2 response develops characterized by high levels of IL-4, IL-5, and IL-13 which decreases when the infection enters the chronic stage." (PMID 20537152, 2010).
infection (continued). "By contrast, regulatory or alternatively activated macrophages, for example those activated by IL-4, fail to control the infection being super-infected." (PMID 20169081, 2010). "In cattle, a more complex Th1/Th2-mixed cytokine pattern involving production of IFNγ and IL-4 has been reported during infection with Ostertagia ostertagi." (PMID 20356390, 2010). "After H strain infection, the expression levels of IL-4, IL-13 and IL-10 in the bursa of chickens were up-regulated and peaked at 3 dpi and then declined at 5 dpi." (PMID 21143846, 2010). "The expression of IL-4 mRNA was 82% higher in paracoccin-activated spleen cells from male compared with those from female mice, collected at day 30 post-infection." (PMID 20505765, 2010). "Transcript levels for various cytokines/chemokines (KC [CXCL1], MCP-1 [CCL2], MIP-1α, IFN-γ, IL-4, IL-5, IL-6 and IL-10) were determined in lungs of infected mice on days 1, 6 and 9 post-infection." (PMID 20661429, 2010). "Infection of macrophages by primary R5X4 and X4 isolates of HIV-1 is inhibited by IL-4 and IL-13, an effect that is associated with down-regulation of surface CXCR4, CCR5 and CD4 expression." (PMID 20380696, 2010). "Infected cells were collected 24 and 48 h post infection and total RNA was isolated for detection of the IL-4 transcript by TaqMan RT–PCR as described in the Methods." (PMID 21139679, 2010). "Similar to this study, in another study, IL-4 expression by a recombinant vaccinia virus exacerbated infection and the IL-4-induced exacerbation was T cell independent." (PMID 21139679, 2010). "IL-4 can also act on APCs to polarize them during an active infection and it has been shown to up-regulate CD86 on human alveolar macrophages via ERK1/2 and JAK/STAT6 pathways." (PMID 21054882, 2010). "A significantly induced Th2 response as evaluated by a significant increase in IL-4 production by polyclonally activated spleen T cells was found in the 7 weeks infection state as compared to the 2 weeks infection state and to mice not infected." (PMID 20537152, 2010). "Faced with the persistance of P46 overexpressing L. major in C57BL/6 mice, we tested cytokine production in draining lymph nodes 17 days post infection, using IL-4 and IFNγ sandwich ELISA." (PMID 20345655, 2010). "Increased susceptibility to C. parvum infection in mice after treatment with anti-IL-4 antibodies, or in mice lacking either an IL-4 gene or the gene for the IL-4 receptor, supports the role of IL-4 cytokine in the control of infection." (PMID 19247447, 2009). "We have previously shown that infection of macrophages with L. major parasites strongly synergizes with IL-4 to increase arginase activity and we have shown that the arginase measured was mainly host arginase." (PMID 19597544, 2009). "Significant between-group differences were evident throughout the observation period, with maximum values reached at day 10 after infection of 3.2 ± 0.5 in IL-4−/− mice versus 2.0 ± 0.3 in wt animals." (PMID 19606256, 2009). "On the contrary, serum levels of proinflammatory cytokines were similar in both groups, except for TNF-α production which was significantly higher in IL-4−/− mice with respect to controls (52 ± 10 versus 11 ± 5 pg/mL of serum) at day 2 after infection." (PMID 19606256, 2009). "For example, infection with F. hepatica induces potent Th2 responses, characterised by production of IL-4, IL-5 and IL-10." (PMID 19478853, 2009). "We observed that IL-10 expression was up-regulated 4- fold at 5 h and 90-fold at 24 h post-infection (p.i.), while expression of IL-4, IL-13 and another immunosuppressive cytokine, TGF-β, were not significantly altered at both time points (data not shown)." (PMID 19816558, 2009). "In fact, infection with 107 GBS per mouse resulted in a 10% mortality in IL-4−/− mice, while 40% of wt mice had died at the end of observation period." (PMID 19606256, 2009).
infection (continued). "IL-2, IL-4, IL-5 levels on day 4 were significantly lower than the levels in moribund animals or in animals on day 11 post-infection (p < 0.001, Bonferroni corrected)." (PMID 19250545, 2009). "In Se-adequate mice, the immune response appeared to be dominated by both Th1 and Th2 cytokines, as evident by increased expression of IFN-γ, IL-2, and IL-4 during the early stages of infection." (PMID 19247447, 2009). "Early expression of IL-4 along with IFN-γ observed in Se-adequate mice has also been shown to be upregulated following infection of C. parvum." (PMID 19247447, 2009). "In control (PBS) group, IL-4 levels on day 21 and 35 ranged from 32 to 50 pg/mlbut on challenge infection, IL-4 levels were significantly enhanced." (PMID 19956549, 2009). "WT mice displayed significant increases in Retnla, Il4, Il5, Il13, and Ccl11 (Eotaxin) mRNA expression following infection with N. brasiliensis, while Il25 and the mucin genes Muc5ac and Gob5 were not altered." (PMID 19381262, 2009). "Blockade of activated T CD8 death increased IFN-γ secretion in initial stages and IL-4/IL-10 secretion in latter stages of infection." (PMID 19582140, 2009). "By contrast, the production of helminth-specific Th2 cytokines, such as IL-4 and IL-5, was suppressed by infection with T. gondii." (PMID 19478853, 2009). "Enhanced protection from infection was also demonstrated for IL-2 and IL-4 CYT-IVAC vaccinated mice further illustrating the adjuvant effect of membrane-bound IL-2 and IL-4." (PMID 19393093, 2009). "We evaluated Th1 cell immunity in immunized mice after vaginal challenge by quantitating the number of CD3+CD4+ cells that secrete IFNγ or IL-4 in iliac lymph nodes (ILNs) during peak infection (day 7) and during resolution of infection (day 15)." (PMID 19404403, 2009). "Taken together, the quality of cytokine responses in different vaccine groups represented production of IFN-γ, IL-12 and IL-4 before infection which correlated with the decreased parasite level in post infection." (PMID 19503834, 2009). "The study of the cytokine profiles from the supernatant of proliferated MLN cells revealed that Se-adequate mice produced higher levels of Th1 (IFN-γ and IL-2) and moderate amounts of Th2 (IL-4) cytokines throughout the course of infection." (PMID 19247447, 2009). "Experiments performed herein also demonstrated that stimulation of three cytokines, IFN-γ, IL-12 and IL-4, before infection correlated with decreased parasite level." (PMID 19503834, 2009). "The infection induced a progressive increase in the levels of IL-4 in BAL and in serum in both experimental groups; however, IL-4 values in the L. casei mice were significantly higher than those in the control group." (PMID 19835595, 2009). "This shows that for both infection regimes there were convex relationships with time p.i. for the concentration of IL4 and IL13 produced by MLN cells stimulated with parasite antigen and for the concentration of anti-S." (PMID 18575588, 2008). "Previous reports on this cohort have suggested that elevated IL-4 mRNA expression in household contacts correlates with heightened immune responsiveness to ESAT-6–a good proxy for infection." (PMID 18231607, 2008). "As IgE and eosinophils are highly dependent on IL-4, Il-5 and IL-13, it was thought that protection against infection by Schistosoma would involve a Th2 immune response." (PMID 19471606, 2008). "Infection levels by Schistosoma are controlled by a major locus on chromosome 5q31-q33 containing the IL4, IL5 and IL13 genes related to the Th2 immune response." (PMID 19471606, 2008). "Infection levels are mainly regulated by a major locus SM1, in 5q31-q33 region, which contains the genes encoding for the IL-4, IL-13, and Il-5 cytokines." (PMID 19471606, 2008). "We observed some small quantitative immunological differences between different infection regimes, in which the concentration of IL4, IL13, anti-S." (PMID 18575588, 2008).
infection (continued). "We found that both infection regimes resulted in Th2-type immune response, characterised by IL4 and IL13 produced by S. ratti stimulated mesenteric lymph node cells, anti-S." (PMID 18575588, 2008). "Levels of IL-10 rose to peak with infection intensity in 11–12 year olds, while levels of IL-4 and IL-5 rose more slowly peaking later in 15–16 year olds." (PMID 18045464, 2007). "No clear pattern was observed with TH1 cytokines however, expression of IL-4 was 50-times higher in LNs of sensitized mice at 36 h post-infection." (PMID 18000543, 2007). "Concentrations of Th-2 cytokines (IL-4, IL-5, and IL-13) as well as expression all the genes (IL-4, IL-5, and IL-13) were found to be greater (p < 0.05) in resistant sheep on different days post infection." (PMID 41993907, 2026). "However, the infection predominantly induces a Th2‐biased immune profile, characterized by elevated levels of IL‐4, IL‐5, IL‐10, IL‐23, and IL‐13, which appears to support parasite survival within the host." (PMID 41503693, 2026). "IL-6, IL-4, and CRP may work as risk indicators of developing joint pain and chronic arthritis after the infection’s acute phase." (PMID 41598488, 2026). "IFN‐γ, known for its anti‐inflammatory, antiviral, and immunomodulatory functions, is essential for infection control, and elevated IFN‐γ levels post‐SLIT have been associated with positive treatment responses in AR, often paired with a decreased IL‐4/IFN‐γ ratio." (PMID 39739782, 2025). "Eosinophils, basophils, and mast cells are known to play a key role in the initiation and regulation of Th2 responses; these cells may be promptly recruited to infection sites and draining lymph nodes in order to produce IL-4 and/or IL-13." (PMID 40150023, 2025). "In addition, interleukin (IL)-2, granulocyte-monocyte colony stimulating factor (GM-CSF), granzyme B, IFN-γ, and IL-4 were specifically released in response to infection with MeVac-VLQSQRTD and MeVac-SGKALVLQSQRTD." (PMID 41050431, 2025). "The high concentration of IL-4 associated with low levels of IFN-γ observed in the group infected with the hybrid parasite and L. (V.)guyanensis has been described in other studies; however, it is classically associated with a progressive infection scenario." (PMID 41017914, 2025). "TSLP release in response to RV infection and stimulation with IL-4 was significantly increased in asthmatic BECs as compared with healthy BECs, and the same was observed after stimulation with IL-4 and IL-13 on top of infection with RV." (PMID 40370530, 2025). "The present study also found that changes in CSF levels of IL-4 and IL-12p70 positively correlates with cognitive flexibility deficits, suggesting that immune response to mild infection may explain the severity of PASC-like symptoms in RMs." (PMID 41377983, 2025). "Additionally, Type 2 cytokines such as IL-4 and IL-13 were also present in the primary infection mice at these two time points, and with significantly higher IL-5 expression at 7 DPC than all other groups." (PMID 41190814, 2025). "In addition, we observed significant changes in the levels of IFN-γ, IL-4, and IL-17A during the early stages of infection, while the inhibitory cytokine IL-10 exhibited a significant increase in the later stages." (PMID 40742129, 2025). "Thus, IL4 treatments decrease pathogen density in at least three infection models, likely via the same mechanism." (PMID 40667878, 2025). "Transforming growth factor β (TGF-β), interleukin (IL)-10, and IL-4 were neutralized upon infection with mouse-adapted SARS-CoV-2 (CMA3p20), a model of mild disease; lung inflammation was quantified by histology and flow cytometry at early and late time points." (PMID 40854598, 2025). "Levels of IL-17A and IL-4 were unaffected by infection or CX3CL1 receptor inhibition." (PMID 40936920, 2025).
infection (continued). "The role of IL-4 has been questioned following evidence that it stimulates dendritic cells from BALB/c mice to produce IL-12 in the presence of Leishmania (Leishmania) major during the early stages of infection." (PMID 41017914, 2025). "As expected from our earlier studies, IFN-γ applied to BALB/c mice for the first 5 days of infection resulted in stronger Th2/1 hybrid responses, evident in the more prominent IFN-γ production and diminished IL-4 expression of GATA-3+ T cells isolated from IFN-γ treated mice at day 6 post infection." (PMID 39910093, 2025). "Heterologous infection of wild-type mice significantly increased mRNA expression of Il4, Il5, Il13." (PMID 41573550, 2025). "Contrary to what occurs in animals whose predominant profile is Th2, characterised by higher amounts of IL‐4, IL‐5, IL‐10 and TGF‐β and cells with a lower capacity to destroy the protozoan and, therefore, responsible for a greater susceptibility to infection and the appearance of clinical signs." (PMID 40033570, 2025). "Collectively, these data support a role for IL-4 in regulating lung pathology in this infection." (PMID 40854598, 2025). "Interestingly, H99 infection resulted in a slightly elevated level of IL-4, whereas Mu-1 infected mice exhibited the highest levels of IFN-γ among the strains tested (57, –, 59)." (PMID 41020608, 2025). "It has been demonstrated that BALB/c mice produce IL-4 early following infection." (PMID 40502169, 2025). "Importantly, during the later phase (7 days post-infection), there was a significant upregulation of M2-/Th2-related markers, including Arg-1, IL-4, and IL-10, in K. pneumoniae_OMVs-immunized mice relative to the PBS group." (PMID 41472051, 2025). "Given the critical role of IL‐2 and IFN‐γ in anti‐infective immunity, their elevation may indicate enhanced resistance to infection, while increased IL‐4 may reflect modulation of inflammation." (PMID 41190418, 2025). "The infection stimulates T helper 2 lymphocytes, which produce interleukins (IL)-4 and IL-10." (PMID 40421174, 2025). "Key findings revealed that interleukin-4 (IL-4), a protein driving immune defense against parasites, was strongly associated with infection in adults but not children." (PMID 40526709, 2025). "In accordance with the drainage of the upper SI shared between MLN and CLN, both sites comprised significantly elevated and similar frequencies of IL-4 and IL-13 competent Th2 cells during larval development (day 6 p.i.)and after transition to the patent stage of infection (day 14 p.i.)." (PMID 40092986, 2025). "Allergic sensitization by viral antigens is a result of the Th2-biased response which occurs at early stages of the infection and is characterized by early onset of IL-4 production (4 days post-inoculation) and antiviral IgE production, which correlated with severity of the disease symptoms." (PMID 40261882, 2025). "HBoV1 infection increases the concentrations of IL-2, IL-4, IL-10, and IL-13 in patients." (PMID 39846742, 2025). "The lower IL-4 responses compared to IFNγ further confirm a predominantly Th1-skewed immune response induced by vaccination, consistent with the profile observed during self-limiting natural infection and previous HEV239 findings." (PMID 40733519, 2025). "IL-4 is an important inflammatory factor involved in enhancing B-cell activity against infection." (PMID 38915037, 2024). "This is the first report on the differences in responses of IL-4 and IL-6 to concomitant infection." (PMID 39195804, 2024). "We have previously observed an upregulation of the gene encoding IL-4 in BALB/c resident peritoneal macrophages in response to infection with L. panamensis, but no changes were found in IL-4Rα expression levels." (PMID 39830895, 2024). "Taken together, these data suggest that mice with basophils deficient for IL-4 and IL-13 failed to control bacterial translocation into the blood during infection and this was not dependent on a lack of neutrophil activation." (PMID 38780542, 2024).